MMP9 (matrix metallopeptidase 9)
Diseases named in the same sentence as MMP9 in open-access papers (continued):
Sharing a sentence is not in itself a finding about the gene and the disease.
periodontitis (continued). "The PACs also inhibited the secretion of the metalloproteinases MMP-3 and MMP-9 that actively participate in the destruction of oral tissue in periodontitis, and prevented the activation of the NF-κB signaling pathway that plays a key role in inflammatory processes." (PMID 41002732, 2025). "Importantly, elevated levels of IL-1β and MMP-9 are correlated to periodontitis, with higher levels found in periodontitis compared to healthy individuals." (PMID 41303313, 2025). "Additionally, levels of certain inflammatory markers, such as PCR, IL-6, and MMP-9, were significantly higher in serum in patients with EA and chronic periodontitis, suggesting a systemic inflammatory state." (PMID 40231144, 2025). "Gingival epithelial cells may contribute to tissue responses in periodontitis through the secretion of MMP-9 in response to PAMPs." (PMID 40281482, 2025). "Elevated levels of MMP-9 were observed in periodontitis patients compared with healthy subjects." (PMID 39200004, 2024). "In addition, the group that received antibiotics and enzyme Est816 showed reduced expression of MMP-9 compared to the periodontitis group; however, the individual effects of enzyme Est816 and MMP-9 were far less pronounced than their combined effect." (PMID 38779565, 2024). "Matrix metalloproteinase (MMP)-9 is one of the proteinases targeting type I collagen in periodontal ligaments, leading to the degradation of extracellular matrix proteins and the propagation of periodontitis." (PMID 39064296, 2024). "Also, they revealed that MMP-2 mRNA was virtually absent in the periodontitis groups, but present in some gingivitis-affected tissues and healthy controls; MMP-9 transcripts were more frequently detected in periodontitis samples." (PMID 38474009, 2024). "Some articles have exhibited upregulated MMP-9 in gingival crevicular fluid (GCF) during the early stages of periodontitis, which may consider MMP-9 a predictor of early disease activity." (PMID 39350180, 2024). "Moreover, a higher MMP-9 concentration in serum and saliva has been found in patients with periodontitis and cardiovascular diseases." (PMID 37510279, 2023). "Experimental periodontitis also increased MMP-9 levels in the gingiva of WT mice." (PMID 38156070, 2023). "The mean value of MMP9 in the DS group with chronic periodontitis is 18.6455, which is statistically significant (p<.001) compared to the mean values of 19.8540 in systemically healthy subjects with chronic periodontitis and 25.2505 in systemically healthy controls." (PMID 37448427, 2023). "All tested biomarkers (MMP-8, MMP-9, and TIMP-1) and ratios of MMP-8/TIMP-1 and MMP-9/TIMP-1 showed statistically significant diagnostic accuracy in differentiating between periodontal health and periodontitis." (PMID 36292174, 2022). "Among the MMP isoforms, MMP-9 has been validated in various preclinical models as one of the most common mediators present in the stages of inflammation progression in patients with periodontitis." (PMID 35163727, 2022). "The non-alcohol-drinking participants with C allele of MMP-9 C-1562T, as compared to T allele, were less susceptible to aggressive periodontitis (adjusted OR = 0.4; 95% CI = 0.18–0.90)." (PMID 35454140, 2022). "Studies have been carried out on salivary MMP-8 and crevicular MMP-2, which were known to serve as biomarkers of periodontal disease; however, there is a dearth of literature on how type-II diabetes mellitus (type-II DM) influences the levels of MMP-9 in chronic periodontitis patients." (PMID 35408573, 2022). "MMP-9 (or the gelatinase B) participates in the breakdown of various proteins from the connective tissue, including collagen type IV, V, and XI, proteoglycans, and elastin and is abundantly expressed in chronic periodontitis (CP)." (PMID 35163727, 2022). "It was suggested that MMP-2 T-790G, MMP-9 C-1562T, and TIMP-2 G-418C gene polymorphisms might be associated with periodontitis in the Taiwanese Han population." (PMID 35454140, 2022).
periodontitis (continued). "In addition, periodontal disease has been closely linked to high levels of NO, indicating a direct correlation between serum NO, MMP-9, and periodontitis." (PMID 35163727, 2022). "To compare PIL landscape-based risk classification with traditional biomarkers for periodontitis, we performed a head-to-head comparison and found that the protein levels of IL-1β, MMP-9, and IL-10 in the PICF do not predict peri-implantitis outcomes." (PMID 34093848, 2021). "The present study was hence planned to estimate the effect of locally delivered melatonin gel as an adjunct to nonsurgical periodontal therapy on the clinical parameters (PD, CAL, PI, and GI) as well as TAC and MMP-9 levels in GCF of stage II periodontitis patient." (PMID 33628250, 2021). "Among MMP isoforms, metalloproteinase-9 (MMP-9) has been validated in various pre-clinical models as one of the most frequent mediators present in tissues during the active stages of inflammation progression in patients with either periodontitis or CVD." (PMID 33810003, 2021). "Furthermore, the results show that the combined presence of periodontitis and CVD resulted in a synergistic effect on potentially hs-CRP-mediated MMP-9 levels compared to subjects with periodontitis and healthy subjects." (PMID 33810003, 2021). "Two functional polymorphisms in the matrix metalloproteinase-2 and -9 (MMP-2 and MMP-9) genes may contribute to periodontitis pathogenesis." (PMID 31497543, 2019). "Still, there is some controversy over whether salivary MMP-9 levels are higher in patients with periodontitis." (PMID 30726210, 2019). "Therefore, Mmp9 elevation in gingival tissue also participates in inflammation in mouse model of ligature-induced periodontitis." (PMID 31605018, 2019). "This confirms that MMP-9 can function as a marker for the progression of periodontitis." (PMID 30246792, 2018). "The roles of MMP‐2, MMP‐8, MMP‐9, and MMP‐12 have been analyzed with respect to the genetic polymorphisms; they may contribute to the susceptibility to periodontitis." (PMID 29744169, 2016). "In conclusion, this meta-analysis with published data suggested that the MMP-2-753 C/T, MMP-3-1171 A5/A6, and MMP-9-1562 C/T polymorphisms were associated with periodontitis susceptibility and there is lack of association between the MMP-8-799 C/T polymorphism and periodontitis." (PMID 27095260, 2016). "As periodontitis and aorta aneurysms share MMP-9 as a pathological enzyme and as a biomarker, we wanted to know if the same bacteria could be involved in both diseases." (PMID 26110102, 2015). "MMP-9 could be actively involved in the extracellular matrix degradation in apical periodontitis lesions." (PMID 25821836, 2015). "Attempts with inhibitors of MMPs have already been successful in a treatment of periodontitis; therefore, there is a rational possibility that selective inhibitors of MMP-9 could find application also in the treatment of IBD." (PMID 24803722, 2014). "This study identified some 20 proteins which were differentially expressed in periodontitis saliva and most, including MMP-8, MMP-9, α2-macroglobulin, and complement C3, have previously been identified as potential biomarkers in conventional analysis of periodontitis saliva." (PMID 24944840, 2014). "Indeed, MMP-9 levels in gingival crevicular fluid have been used to identify the stage of periodontitis." (PMID 25610476, 2014). "An increased risk of developing periodontitis is associated with genetic polymorphisms of IL1A, IL1B, IL6, and TNFA genes and MMP-9 (−1562C/T), ANRIL rs1333048, rs1333042, rs2891168, and rs496892 polymorphisms might have impact on susceptibility to periodontitis, especially in Caucasian individuals." (PMID 41300760, 2025).
periodontitis (continued). "Based on our above studies in network pharmacology and molecular docking, we screened and predicted that Kaempferol treatment exhibits a high binding affinity for IL6, CASP3, and MMP9, suggesting that these proteins may be the primary targets of Kaempferol in the treatment of periodontitis." (PMID 40004956, 2025). "Salivary and plasma levels of IL-1β, IL-6, and TNF-α increase with periodontal disease severity, and plasma MMP-8 and MMP-9 levels decrease after non-surgical periodontal treatment events, supporting the theory of periodontitis causing increased systemic inflammation." (PMID 38672972, 2024). "Considering that F. nucleatum subspecies stimulated a considerably higher release of MMP-9 from neutrophils and that MMP-9 seems to be highly expressed early in periodontitis, future studies could focus on correlations between MMP-9 level and number of F. nucleatum ssp." (PMID 39450334, 2024). "Similarly, the mean value of MMP9 in the DS group with chronic periodontitis was 18.6455, which was statistically significant (P<.001) compared to the mean values of 19.8540 in systemically healthy subjects with chronic periodontitis and 25.2505 in systemically healthy controls." (PMID 37448427, 2023). "The mean difference in MMP9 in the DS group with chronic periodontitis showed highly statistically significant levels of 5.39650 compared to 1.20850 in the systemically healthy group with chronic periodontitis and -6.60500 in the systemically healthy control group." (PMID 37448427, 2023). "Thus, high MMP-9 levels may accurately reflect the condition of patients with periodontitis and can be a useful biomarker for diagnosis." (PMID 35163727, 2022). "The exploratory hypothesis was that pre-pregnancy BMI would be independently associated with changes during pregnancy and early postpartum in inflammatory markers (CRP, IL-6, and MMP-9) and anti-inflammatory cytokine (IL-10) concentrations in pregnant women with periodontitis." (PMID 35270396, 2022). "Moreover, the expression levels of malondialdehyde (MDA), MMP-9, and cardiac Troponin-T (cTnT) in cardiac left ventricular tissue were upregulated in experimental periodontitis rats, and could be downregulated remarkably by melatonin." (PMID 36498871, 2022). "The ROC curve showed that MMP-8, MMP-9, TIMP-1, MMP-8/TIMP-1, and MMP-9/TIMP-1 had statistically significant diagnostic accuracy, with areas under the curve (AUCs) of 0.892, 0.844, 0.920, 0.986, and 1.000, respectively, when distinguishing periodontitis from the controls." (PMID 36292174, 2022). "However, little is known about the relationship between BMI and the dynamics of the concentrations of other inflammatory biomarkers, such as interleukins and MMP-9 in the context of pregnancy, and even less is known about these relationships in pregnant women with periodontitis." (PMID 35270396, 2022). "The MMP-9-1562C > T polymorphism showed a significant association with the risk of periodontitis among Caucasians and the chronic periodontitis/aggressive periodontitis subgroup, whereas MMP-2-753C > T polymorphism was significantly associated with periodontitis risk only among Asians." (PMID 35454140, 2022). "As a result, it can be estimated that these elevated levels of MMP-9 in type-II DM are one of the important factors responsible for the periodontal destruction in diabetic subjects and, if controlled, the severity of chronic periodontitis may be reduced in diabetic subjects." (PMID 35408573, 2022). "In this regard, recent studies validated MMP-9 as an essential modulator of the host’s defense mechanisms during the initial immune phase, which in turn influences, in a cascade, the entire host defense mechanism, endothelial homeostasis, and finally, CVD and periodontitis risk." (PMID 33810003, 2021).
periodontitis (continued). "Furthermore, the reason for the different expression between serum and salivary MMP-9 may be due to the different concentration of NO between the oral and systemic environment, in which the impact of periodontitis can have different effects." (PMID 33810003, 2021). "Therefore, calcitriol intervention could be a useful measure to attenuate bone resorption in periodontitis by reducing NFATc1 and MMP‐9." (PMID 32406154, 2020). "In addition, several MMPs are linked together where MMP-13 could be involved in the degradation of soft and hard support tissues and the activation of pro-MMP-9 during the progression of chronic periodontitis." (PMID 33294463, 2020). "MMP-2 -753C>T and MMP-9 -1562C>T polymorphisms may not be associated with periodontitis risk in overall analysis." (PMID 31497543, 2019). "MMP-2-753C>T and MMP-9-1562C>T polymorphisms may not be associated with risk of periodontitis in overall population." (PMID 31497543, 2019). "Therefore, this higher identifiable activity of MMP-13 in Marfan samples indeed could be associated to the degeneration of soft and hard tissues by pro-MMP-9 activation during progression of chronic periodontitis." (PMID 31340803, 2019). "However, all MMP-9 isoforms were detected in periodontitis patients’ oral cavity." (PMID 26110102, 2015). "In patients with periodontitis, the expression and activation of MMPs, especially MMP-8 and MMP-9, significantly influence tissue degradation." (PMID 41002732, 2025). "In patients with moderate to advanced periodontitis, GCF MMP-9 and MMP-13 levels have been shown to be significant predictors of disease progression over a two-month monitoring period." (PMID 41328144, 2025). "Protein–protein interaction (PPI) network analysis identified ESR1, MMP2, MMP9, MMP13, and STAT1 as hub genes, highlighting their central role in EGCG-mediated modulation of periodontitis." (PMID 41009706, 2025). "Minocycline, an MMP-9 inhibitor, also limited EAE progression, while doxycycline, which reduces collagenase activity, has been approved for the treatment of chronic periodontitis." (PMID 41226358, 2025). "Recent evidence highlights several molecular mediators involved in the pathogenesis of periodontitis namely estrogen receptor 1 (ESR1), matrix metalloproteinases (MMP2, MMP9, MMP13), and signal transducer and activator of transcription 1 (STAT1)." (PMID 41009706, 2025). "By integrating these results with Gene Ontology, pathway, and disease enrichment analyses, it was determined that ESR1, MMP2, MMP9, MMP13, and STAT1 are potential key targets of EGCG in the context of periodontitis treatment." (PMID 41009706, 2025). "From healthy to severe periodontitis, the expression of IL-1β, IL-6, IL-8, TNF and MMP-9 gradually increased, but the E–P interaction scores remained constant, suggesting a persistent epigenetic regulatory footprint." (PMID 40902506, 2025). "The theory of the indirect effects of periodontitis on premature or low birth-weight births involves elevated levels of matrix metalloproteinase-8 (MMP-8) and matrix metalloproteinase-9 (MMP-9)." (PMID 38672972, 2024). "The authors concluded that several MMPs, particularly MMP-1, MMP-2, MMP-9, and MMP-13, are involved in gingival ECM degradation during periodontitis." (PMID 38474009, 2024). "Meta-analysis performed for salivary biomarkers showed the highest sensitivity for the diagnosis of periodontitis for IL-1β (77.8%) and MMP-8 (72.5%), and the highest specificity for MMP-9 (81.5%) and IL-1β (78%)." (PMID 39684335, 2024). "Osteocalcin (OC), IL-1β, tumor necrosis factor-alpha (TNF-α), interleukin-6 (IL-6), OPG, and matrix metalloproteinase-9 (MMP-9) were significant in oral fluid or saliva, and they were from periodontitis, MRONJ, and osteoporosis." (PMID 39410587, 2024). "In periodontitis, activated monocytes and lymphocytes release matrix metalloproteinases (MMP), particularly MMP-9, an enzyme responsible for bone formation." (PMID 37378834, 2024).
periodontitis (continued). "Similar alterations were observed in the longitudinal experimental periodontitis model across all age groups with elevated MMP1, MMP3, MMP9, and ALPL." (PMID 38098978, 2023). "Periodontitis and CKF show genetic cross-talk, which is supported by five hub genes, i.e., CCL5, FCGR3B, MMP-9, SAA1, and SELL." (PMID 37510279, 2023). "MMP‐8 and MMP‐9 can be detected in GCF collected via intracrevicular washing and can be used as markers for T. denticola growth in periodontitis." (PMID 36414019, 2023). "Previous studies have demonstrated the relevance of MMP-2 and MMP-9 in periodontal diseases and increased MMP-13 activity in both murine model of periodontitis and human periodontitis." (PMID 38152410, 2023). "The third potential hub cross-talk gene between periodontitis and CKF was MMP-9, a multidomain enzyme, which is excreted by neutrophils among other inflammatory cells, which is induced by many pro-inflammatory cytokines." (PMID 37510279, 2023). "DS periodontitis patients showed a positive correlation with highly statistically significant values (p< .000) and increased MMP8 and MMP9." (PMID 37448427, 2023). "Meanwhile, the AUCs between periodontal health and periodontitis S1 for MMP-8, MMP-9, and TIMP-1 were 0.964 (p value = 0.0001), 0.938 (p value = 0.001), and 0.902 (p value = 0.002), respectively." (PMID 36292174, 2022). "A recent study demonstrated that periodontitis enhanced the levels of proinflammatory cytokines (TNF-α and IL-1β), oxidative stress (MDA), and proteases (MMP-8, MMP-9, and cathepsin D) in rat kidneys, while melatonin suppressed them significantly." (PMID 36498871, 2022). "Periodontitis was found to predict increased MMP-9 and tissue inhibitor of matrix metalloproteinases (TIMP-1) and their ratio MMP-9/TIMP-1." (PMID 35448062, 2022). "The study results identified a tremendous increase in the levels of MMP-8 and MMP-9, and a decrease in the level of MMP-2, in cases of periodontitis." (PMID 35626325, 2022). "In particular, MMP‐8, MMP‐9, and, to a lesser extent, MMP‐14 have been studied in relation to periodontitis." (PMID 34850390, 2022). "In the current study, selected salivary biomarkers (MMP-8, MMP-9, and TIMP-1) showed high sensitivity to discriminating periodontitis from periodontal health when used alone or in combination." (PMID 36292174, 2022). "Based on available evidence, this study aimed to examine the ability of salivary MMP-8, MMP-9, and TIMP-1, individually or in combination, to diagnose periodontitis and to discriminate periodontitis S1 to S3." (PMID 36292174, 2022). "Then, to know if the upregulation of MMP-9 in the GCF of patients with rosacea is due to this disease, a multiple regression model adjusted for periodontitis, smoking, and age was performed." (PMID 36077255, 2022). "Studies have detected higher levels of MMP-9 in the GCF and serum of individuals with periodontitis compared to healthy individuals." (PMID 36077255, 2022). "In summary, the ROC analyses showed that the AUCs for salivary MMP-8, MMP-9, and TIMP-1 were 0.892, 0.844, and 0.920, respectively, between periodontal health and periodontitis." (PMID 36292174, 2022). "For discriminating gingivitis vs periodontitis groups, the predictor variables resulting from the CART analysis included HGF, TIMP-1, MMP-9/TIMP-1 ratio and OPG." (PMID 33742017, 2021). "For discriminating health vs periodontitis groups, the predictor variables resulting from the CART analysis included HGF, MMP-9, LBP and IL-1b." (PMID 33742017, 2021). "Matrix metalloproteinase‐8 (MMP‐8), MMP‐9, and tumor necrosis factor alpha (TNF‐α) levels were higher in periodontitis and in RA and MMP‐8 levels increased with the severity of periodontitis." (PMID 33954982, 2021).